CACNA1C (calcium voltage-gated channel subunit alpha1 C)
Diseases named in the same sentence as CACNA1C in open-access papers (continued):
Sharing a sentence is not in itself a finding about the gene and the disease.
developmental delay (6 papers, 2021 to 2025). "In this study, we report a child with a de novo heterozygous missense variant (c.1973T > C; L658P) in CACNA1C, presenting with refractory epilepsy, global developmental delay, hypotonia, and multiple systemic abnormalities, but without overt cardiac dysfunction." (PMID 40133997, 2025).
leukemia (6 papers, 2011 to 2025). A malignant (clonal) hematologic disorder, involving hematopoietic stem cells and characterized by the presence of primitive or atypical myeloid or lymphoid cells in the bone marrow and the blood. "Overexpression of CaV1.2 (gene CACNA1C) occurs in many cancers including colorectal, gastric, pancreatic, sarcoma, leukaemia, brain, breast, uterus, skin and prostate." (PMID 27342111, 2016). "We also found high expression of CACNA1C in most cancer types, including colorectal, gastric, pancreas, brain, breast, uterus, skin, and prostate cancers and leukemia." (PMID 26147197, 2015). "The Blood database indicated high expression of CACNA1C in leukemia relative to normal samples." (PMID 26147197, 2015). "Thus, we speculated that leukemia patients with high expression of CACNA1S, CACNA1C, or CACNA1A relative to normal samples are likely to experience metastasis of the cancer cells to the lungs, heart, central nervous system, and other tissues." (PMID 26147197, 2015).
long QT syndrome 8 (6 papers, 2015 to 2022). "To date, 16 genes were identified to responsible for LQTS, of which, mutations in CACNA1C is accounted for long QT syndrome 8 (LQT8)." (PMID 30027834, 2018).
congenital heart disease (5 papers, 2014 to 2024). A heart disease that is present at birth. "This congenital heart disease might be produced by several mutations in the CACNA1C gene, encoding the CaV1.2 subunit of the ICaL current." (PMID 38968219, 2024).
neuroblastoma (5 papers, 2013 to 2020). Neuroblastoma (NB) is the most common solid, extracranial childhood tumor. "Using reporter gene constructs we demonstrate the CACNA1C promoter is a major mediator of inducible regulation of CACNA1C activity in the SH-SY5Y neuroblastoma cell line." (PMID 29501388, 2018). "Reporter gene analysis in the SH-SY5Y neuroblastoma cell line demonstrated that the CACNA1C promoter contained both positive and negative regulatory domains within the sequences examined." (PMID 29501388, 2018). "Using CACNA1C promoter deletion constructs to analyse the modulation of a reporter gene in SH-SY5Y neuroblastoma cells, we identified a positive regulator within the region of −399 to −149 at the promoter, and a repressor in the region of −838 to −399." (PMID 29501388, 2018).
cognitive decline (4 papers, 2017 to 2024). "Moreover, future studies should investigate the rationale for L-type calcium channel antagonists as potential agents for preventing cognitive decline in BD type I patients carrying the CACNA1C A allele." (PMID 28398341, 2017).
essential hypertension (4 papers, 2008 to 2025). Hypertension that presents without an identifiable cause. "CaMK4 mediates ER-related calcium overload, while CACNA1C is linked to primary hypertension." (PMID 41019540, 2025).
Hypoglycemia (4 papers, 2021 to 2024). A decreased concentration of glucose in the blood. "Overall, hypoglycemia should be considered a serious life-threatening condition for all individuals with variants in CACNA1C." (PMID 39580446, 2024). "Several of these features, such as gastrointestinal concerns and hypoglycemia, were identified in every group, suggesting that any variant in CACNA1C has the potential to be syndromic." (PMID 39580446, 2024). "Our findings underline that the potential of hypoglycemia warrants careful attention in patients with CACNA1C variants, and such variants should be included in the differential diagnosis of non-syndromic congenital hyperinsulinism." (PMID 35897673, 2022). "To further extend the knowledge about the metabolic consequences of CACNA1C variants, we performed a retrospective analysis of TS patients reporting hypoglycemia." (PMID 35897673, 2022). "Given the critical role of CaV1.2 in beta cell signaling and the marked frequency of hypoglycemia in patients with TS, CACNA1C is a promising candidate gene for screening patients with congenital hyperinsulinism (CHI)." (PMID 35897673, 2022).
ventricular tachycardia (4 papers, 2010 to 2025). A disorder characterized by an electrocardiographic finding of three or more consecutive complexes of ventricular origin with a rate greater than a certain threshold (100 or 120 beats per minute are commonly used). "Mutations in the CACNA1C gene are associated with ventricular tachycardia (VT)." (PMID 27502440, 2016). "The proband inherited both the CACNA1C and ACTC1 variants from his father (III-2), who has HCM and non-sustained ventricular tachycardia." (PMID 41287789, 2025).
viral infection (4 papers, 2011 to 2025). "In addition, CACNA1C and HTR2A‐encoded proteins are involved in viral infections, acting as receptors for influenza virus and JC polyomavirus, respectively." (PMID 34745336, 2021).
B-cell lymphoma (3 papers, 2020 to 2022). "CaV1.2 (CACNA1C) expression was increased in classical Hodgkin lymphoma cell lines when compared to other B-cell lymphoma cell lines." (PMID 36330491, 2022).
brain tumors (3 papers, 2019 to 2022). "Previous studies showed CACNA1C was down-regulated in multiple human cancers, including brain tumors, kidney cancers and lung cancers, suggested its regulatory roles in cancer progression." (PMID 31787999, 2019).
calcification (3 papers, 2022 to 2023). Process by which organic tissue becomes hardened by the physiologic deposit of calcium salts. "Integrative genomic study confirmed calcium signaling pathway genes RUNX2 and CACNA1C are associated with calcific disease." (PMID 35597927, 2022).
Dravet syndrome (3 papers, 2020 to 2025). "Additionally, CACNA1C channels may also be expressed in GABAergic inhibitory interneurons, and their pathogenic mechanisms are similar to the loss-of-function mutations in SCN1A seen in Dravet syndrome." (PMID 41177904, 2025).
glioblastoma (3 papers, 2019 to 2023). The most malignant astrocytic tumor (WHO grade IV). "Among the known benidipine targets, mRNA encoding the L-type Ca2+ channel CACNA1C (Cav1.2) was most abundant in both glioblastoma lines strongly suggesting that the observed benidipine effects were mediated at least in part via inhibition of CACNA1C." (PMID 30669316, 2019). "In summary, our experiments suggest that TTFields modulate Ca2+ signaling in two human glioblastoma cell lines which involves long-lasting activation of L-type Cav1.2 (CACNA1C) and most probably further Cav channels and which was completely suppressed by Ca2+ channel inhibitor benidipine." (PMID 30669316, 2019). "Together, these data suggest CACNA1C is expressed in glioblastoma albeit at variable extent." (PMID 30669316, 2019).
Hyperinsulinemia (3 papers, 2022 to 2025). An increased concentration of insulin in the blood. "Using next-generation sequencing, we identified a novel heterozygous CACNA1C mutation in a patient with congenital hyperinsulinism (CHI) and associated hypoglycemic episodes." (PMID 35897673, 2022).
hypertriglyceridemia (3 papers, 2021 to 2024). A laboratory test result indicating elevated triglyceride concentration in the blood. "Specifically, compared to the control group, the expression of Cacna1c and Cacna1b, which was reported to be downregulated in hypertriglyceridemia subjects with decreased insulin secretion, was decreased in HFD mice." (PMID 38557554, 2024). "Meanwhile, compared with the control group, the GSEA results found that CACNA1C was a core gene and the expression of it was decreased in hypertriglyceridemia subjects with T2DM." (PMID 36901708, 2023).
Insulin resistance (3 papers, 2012 to 2021). Increased resistance towards insulin, that is, diminished effectiveness of insulin in reducing blood glucose levels. "Then, we assessed the expression of an upregulated gene map2k6 and downregulated genes cacna1c and cacna1d by insulin resistance." (PMID 34358068, 2021). "In contrast, the expression of the cacna1c and cacna1d genes is decreased by insulin resistance." (PMID 34358068, 2021).
ovarian carcinoma (3 papers, 2021 to 2026). A malignant neoplasm originating from the surface ovarian epithelium. "We also show strong correlation of CACNA1C protein expression using immunohistochemistry correlating with COH ovarian carcinomas patients' disease progression." (PMID 42079127, 2026). "This study was aimed to analyze the roles of CACNA1C in ovarian cancer (OC) of overall survival (OS) and to explore its relationships with immunity." (PMID 34210324, 2021). "CACNA1C could be a prognostic predictor in ovarian cancer, and its overall survival was equally significant in HCC." (PMID 35321246, 2022).
alcohol abuse (2 papers, 2021 to 2022). The use of alcoholic beverages to excess, either on individual occasions ("binge drinking") or as a regular practice. "Another polymorphism (rs1034936) in the CACNA1C gene appears to correlate with alcohol abuse in bipolar patients." (PMID 36238190, 2022).
ameloblastoma (2 papers, 2022 to 2024). The most common odontogenic tumor, arising from the epithelial component of the embryonic tooth and usually affecting the molar-ramus region of the mandible or maxilla. "In the present study, comparative transcriptome profiling of two representative odontogenic lesions, ameloblastoma and odontogenic keratocyst, revealed that Cav1.2 (CACNA1C, an L-type voltage-gated calcium channel) is strongly enriched in ameloblastoma." (PMID 36057617, 2022).
atherosclerosis (2 papers, 2013 to 2020). A disease characterized by the build-up of fatty material and calcium deposition in the arterial wall resulting in partial or complete occlusion of the arterial lumen. "On the other hand, atherosclerosis related hsa-miR-143-3p targets in VSMCs included CACNA1C, COL1A1, and PTGS2, which are associated with VSMC contraction, extracellular matrix synthesis, and proliferation." (PMID 32397522, 2020). "To establish an association between the disease and CACNA1C splice variation at the level of cell, we have completed the single-gene profiling of the α1C molecular remodeling in VSM cells of an artery caused by atherosclerosis." (PMID 25937960, 2013). "Thus, the switch of the CACNA1C alterative splicing from exon 21 to exon 22 is a molecular signature of the Cav1.2 remodeling of VSM cells to a pathophysiological proliferating state in atherosclerosis." (PMID 25937960, 2013).
cardiac arrest (2 papers, 2019 to 2024). Cessation of breathing and/or cardiac function. "We studied a five‐generation family, in which a CACNA1C variant c.2573G>A p.Arg858His co‐segregates with syncope and cardiac arrest, documenting electrocardiographic data and cardiac symptomatology." (PMID 30345660, 2019).
colorectal cancer (2 papers, 2015 to 2022). A primary or metastatic malignant neoplasm that affects the colon or rectum. "For example, colorectal cancers such as colon adenoma, adenocarcinoma, and rectal adenoma showed significant upregulation of CACNA1C when compared to normal control tissues, with p-values ranging from 2.58E-5 to 7.33E-14 and CACNA1C ranking from 2% to 8%." (PMID 26147197, 2015).
Emotional lability (2 papers, 2019 to 2022). Unstable emotional experiences and frequent mood changes; emotions that are easily aroused, intense, and/or disproportionate to events and circumstances. "In males, the A allele of rs1006737 within CACNA1C was associated with lower resilience and higher emotional lability, but the A allele was associated with stronger resilience and lower emotional lability in females." (PMID 31061683, 2019).
glaucoma (2 papers, 2020 to 2022). Increased pressure in the eyeball due to obstruction of the outflow of aqueous humor. "Our data demonstrate that restoration of Ca2+ homeostasis in pericytes lacking Cacna1c preserved capillary diameter and blood flow in glaucoma, in addition to reducing the likelihood of capillary blockage, to levels found in sham controls." (PMID 35135877, 2022). "Analysis of Ca2+ levels using Fluo-4-AM confirmed lack of glaucoma-induced Ca2+ increase in pericytes from Cacna1c−/− retinas, which displayed basal Ca2+ levels similar to sham controls, whereas substantial intrapericyte Ca2+ levels were detected in Cacna1c+/+ retinas." (PMID 35135877, 2022).
glioma (2 papers, 2019 to 2023). A benign or malignant brain and spinal cord tumor that arises from glial cells (astrocytes, oligodendrocytes, ependymal cells). "miR-204-3p suppressed glioma proliferation through the CACNA1C/MAPK pathway." (PMID 36810326, 2023). "Similarly, CACNA1C mRNA abundance varied considerably in resection specimens of low grade and high grade glioma." (PMID 30669316, 2019).
Glucose intolerance (2 papers, 2018 to 2023). Glucose intolerance (GI) can be defined as dysglycemia that comprises both prediabetes and diabetes. "In mice, Cav1.2 was the only LVGCC and the knockout of CACNA1C was lethal (glucose intolerance and loss of first-phase insulin secretion were observed)." (PMID 36901708, 2023). "Similar to findings for Adrb2 loss, β-cell-specific ablation of Cacna1c suppresses GSIS and elicits systemic glucose intolerance in mice." (PMID 30303066, 2018).
insomnia (2 papers, 2016 to 2024). A sleep disorder characterized by difficulty in falling asleep and/or remaining asleep. "The association between CACNA1C and sleep quality was later replicated in a British cohort, indicating that this may be a relevant gene for insomnia." (PMID 27999387, 2016).
kidney cancer (2 papers, 2019 to 2025). Primary or metastatic malignant neoplasm involving the kidney. "As targets of CCBs, genetically predicted levels of CACNA1C (OR=4.64, 95% CI: 1.13-19.0, p=0.033) and CALM1 (OR=1.37, 95% CI: 1.01-1.85, p=0.045) might increase the risk of kidney cancer." (PMID 40535814, 2025).
lung adenocarcinoma (2 papers, 2021 to 2022). A carcinoma that arises from the lung and is characterized by the presence of malignant glandular epithelial cells. "Genetic alterations in this gene were also shown in lung adenocarcinoma indicating a putative function of CACNA1C in lung cancer." (PMID 33953302, 2021).
memory impairment (2 papers, 2024 to 2025). "In addition, changes in Cacna1c/Cav1.2 expression are correlated with memory impairments." (PMID 39231135, 2024).
prostate carcinoma (2 papers, 2015 to 2023). A carcinoma that arises from epithelial cells of the prostate gland. "We found high CACNA1C expression in prostate carcinoma in comparison to normal tissue in the Cancer research 2002/08/01 database." (PMID 26147197, 2015).
serous ovarian cancer (2 papers, 2024 to 2026). "Regarding the constituents of our 7-gene signature, CACNA1C is overexpressed in high-grade serous ovarian cancer and correlated with prognosis, whereas COL16A1 expression is significantly correlated with progression-free survival in advanced serous ovarian cancer." (PMID 38481252, 2024).
sleep disorder (2 papers, 2024 to 2025). A change from the patient's baseline sleeping pattern, in the hours slept and/or an alteration/dysfunction in the stages of sleep. "We observed 142 associations including at known loci for sleep disorders (e.g. MEIS1, CACNA1C, OLFM4, PAX8 and TCF4)." (PMID 41332830, 2025).
testis cancer (2 papers, 2015 to 2022). "CACNA1F only showed high expression in testis cancer, whereas CACNA1A, CACNA1C, and CACNA1D were highly expressed in most types of cancer." (PMID 26147197, 2015).
torsades de pointes (2 papers, 2022 to 2024). A malignant form of polymorphic ventricular tachycardia that is characterized by heart rate between 200 and 250 beats per minute, and qrs complexes with changing amplitude and twisting of the points. "The downregulation of several key genes encoding subunits of cardiac ion channels we observed such as KCNQ1, KCNH2, and CACNA1C, is in line with findings that show QT prolongation and torsade de pointes in patients treated with protease inhibitors (PI), such as lopinavir and ritonavir." (PMID 35686037, 2022).
Achalasia (1 paper, 2016). A disorder of esophageal motility characterized by the inability of the lower esophageal sphincter to relax during swallowing and by inadequate or lacking peristalsis in the lower half of the body of the esophagus. "We observed a number of sequences involving the calcium signaling pathway (ie, CACNA1C, CACNB2, KCNMA1, CHRM2, CAV1, and NCS1) that were differentially expressed and were able to characterize these genes into possible functions related to achalasia pathogenesis." (PMID 27511445, 2016).
anaplastic large cell lymphoma (1 paper, 2022). Anaplastic large cell lymphoma (ALCL) is a rare and aggressive peripheral T-cell non-Hodgkin lymphoma, belonging to the group of CD30-positive lymphoproliferative disorders, which affects lymph nodes and extranodal sites. "On the other hand, downregulation of CACNA1C transcripts (coding for CaV1.2) was seen in centroblastic lymphoma, CACNA1F (coding for CaV1.4) in anaplastic large cell lymphoma, and CACNA1G (coding for CaV3.1) in mantle cell lymphoma." (PMID 36330491, 2022).
angina (1 paper, 2025). "CACNA1C rs2238032 exhibited significant relationships with creatinine clearance (p-value = 0.022), other medications for chest pain (angina) (p-value = 0.0001), B-blocker and thiazide diuretics (p-value = 0.003), and DM treatment (p-value = 0.006)." (PMID 39859138, 2025).
angioedema (1 paper, 2019). Swelling involving the deep dermis, subcutaneous, or submucosal tissues, representing localized edema. "Interestingly, SNPs in human CACNA1C were recently associated with chronic spontaneous urticaria (i.e., spontaneous episodes of hives and/or angioedema) and antihistamine drug response." (PMID 31645420, 2019).
apraxia (1 paper, 2024). Apraxia is a neurological disorder characterized by the inability to perform tasks or movements, despite having the desire and physical ability to perform them. "We included apraxia in the landscape of the neurological signs and symptoms associated with CACNA1C mutations." (PMID 38790536, 2024). "This review summarizes all the known neurological CACNA1C associated manifestations and expands the related phenotype through a case report of a novel de novo mutation that shows additional neurological manifestations (i.e., apraxia)." (PMID 38790536, 2024). "In general, apraxia is not commonly included in the CACNA1C-related neurologic features, even in the most recent descriptions of the CACNA1C-associated disorders." (PMID 38790536, 2024).
cardiac conduction defect (1 paper, 2024). "Methods and Results: We conducted a systematic review of neurologically-predominant presentations without cardiac conduction defects, associated with CACNA1C mutations." (PMID 38790536, 2024).
cocaine addiction (1 paper, 2025). "Further, there is evidence for an important role of CACNA1C in cocaine addiction." (PMID 40204703, 2025).
congenital hyperinsulinism (1 paper, 2022). "Thus, the CACNA1C gene is a promising candidate for screening in patients with dysregulated insulin secretion, e.g., congenital hyperinsulinism (CHI)." (PMID 35897673, 2022).